MCM6 (minichromosome maintenance complex component 6)
Diseases named in the same sentence as MCM6 in open-access papers (continued):
Sharing a sentence is not in itself a finding about the gene and the disease.
glioma (7 papers, 2020 to 2024). A benign or malignant brain and spinal cord tumor that arises from glial cells (astrocytes, oligodendrocytes, ependymal cells). "Minichromosome maintenance complex components (MCMs), consisting of MCM2 - MCM10, are defined as critical diagnostic and prognostic markers, while MCM6 serves as a comprehensive indicator of the poor survival condition of patients with glioma." (PMID 33668040, 2021). "IDH1 mutation, a classical biomarker in glioma, was reported to combinate MCM6 overexpressions to improve the prediction of the prognosis in glioblastomas." (PMID 32089988, 2020). "As an initiator of DNA replication up-regulated in the G0 phase, MCM6 has been identified to serve as a biomarker for undesirable clinical outcomes of patients with endometrial cancer and glioma." (PMID 33668040, 2021). "Univariate and multivariate survival analyses with Cox's regression model present evidence for independent prognostic roles of MCM2 in LUSC prognosis, MCM6 in glioma, MCM5 in lung squamous cell carcinoma, and MCM8 in pancreatic cancer." (PMID 32089988, 2020). "Overexpression of the genes whose transcripts act as potential targets fordysregulated miRNAs in the IDHmut and IDHwt groups is observed in moreaggressive glioma types: FKBP9 – CREB3L4, MCM4, MCM6, PSMB2, ARID1A, ARL4C, GRPEL2, and C9orf64." (PMID 39539523, 2024). "Univariate and multivariate analyses uncovered that MCM2, MCM4, MCM6, MCM7 expression, tumor grade, and age were independent factors that influence the clinical outcome of glioma patients." (PMID 36465369, 2022). "Univariate and multivariate analyses revealed that MCM2, MCM4, MCM6, MCM7 expression and tumor grade, 1p/19q codeletion, primary therapy outcome, and age were independent factors correlated with poor clinical outcomes of glioma patients." (PMID 36465369, 2022). "Univariate and multivariate analyses revealed that MCM2, MCM4, MCM6, MCM7 expression and tumor grade, 1p/19q codeletion, primary therapy outcome, and age were independent factors that influenced the clinical outcome for glioma patients." (PMID 36465369, 2022).
meningioma (7 papers, 2019 to 2024). A generally slow growing tumor attached to the dura mater. "Moreover, high expression of MCM6 was associated with shorter OS in grade II meningioma patients by the Log rank test (p = 0.02) and in all grades of meningioma patients by univariate Cox regression analysis (HR = 1.005, 95%CI 1.002 to 1.008)." (PMID 38758750, 2024). "Meta-analysis of two studies with 154 participants evaluated the association between MCM6 expression and PFS of meningioma patients." (PMID 38758750, 2024). "Further studies on large patient cohorts are needed to evaluate the prognostic value of MCM6 in meningioma patients." (PMID 38758750, 2024). "In conclusion, MCM6 immunohistochemical LI is a relevant prognostic marker in atypical meningiomas, significantly correlated with PFS and OS." (PMID 36672484, 2023). "For grade 2 meningioma, Ki-67 and MCM6 both appear adequate (≥30% for Ki-67, and ≥50% for MCM6, Log-Rank test) for the identification of tissues with potential shorter PFS." (PMID 36672484, 2023). "Using 2 cohorts of 100 grade 1 and 69 grade 2 meningiomas, we compared the prognostic values of Ki-67 and MCM6." (PMID 36672484, 2023). "The aim of this study was to evaluate the prognostic value of MCM6, in comparison with Ki-67, in two series of grade 1 and 2 meningiomas, and to evaluate its correlation with methylation classes." (PMID 36672484, 2023). "In two distinct cohorts of grade 1 and grade 2 meningiomas, we aimed to better clarify the prognostic role of Ki-67 and MCM6, and thus their potential usefulness in clinical practice within grade 1 or grade 2 tumors, in addition to the WHO grading system." (PMID 36672484, 2023). "Our evidence here suggests that MCM6 is a relevant and reproducible marker in atypical meningiomas." (PMID 36672484, 2023). "In atypical meningiomas, the median Ki-67 and MCM6 LI were 20% and 61%, respectively." (PMID 36672484, 2023). "In conclusion, MCM6 is a relevant prognostic marker in atypical meningiomas." (PMID 36672484, 2023). "The aim of this study was to evaluate the prognostic value of MCM6 relative to that of Ki-67 in a series of grade 1 (World Health Organization 2021; n = 100) and grade 2 (atypical) meningiomas (n = 69), using immunohistochemistry, and to evaluate its correlation with methylation classes." (PMID 36672484, 2023). "Hence, we next evaluated the dependencies and the complementarities of these measurements (MI, Ki-67, and MCM6 LI) and derived a DNAm proliferation signature in meningiomas." (PMID 36551712, 2022). "Many studies have shown that the level of expression of MCM6, basing on mRNA detection or immunohistochemistry, was correlated with clinical outcome, e.g., in gliomas, renal cell carcinoma, endometrial adenocarcinoma, lung cancer, osteosarcoma, pheochromocytoma, neuroblastoma, and meningioma." (PMID 36672484, 2023). "Our previous evidence singled out MCM6 as an efficient marker by virtue of its dominant presence in proliferating cells that resulted in striking clear-cut differences in MCM6 labeling index (LI) of the indolent vs. the recurrent meningiomas, with a high reproducibility." (PMID 36672484, 2023). "Before the present study, the specific prognostic value of MCM6 in atypical meningiomas was still not elucidated." (PMID 36672484, 2023). "In a multivariate model, the LI (Labeling Index) of MCM6 correlated with progression free survival of grade 2, but not grade 1 meningiomas." (PMID 36672484, 2023).
meningioma (continued). "In grade 2 meningiomas, but not grade 1, both Ki-67 and MCM6 LIs were correlated with PFS (p = 0.004 and p = 0.005, respectively; Cox univariate analyses)." (PMID 36672484, 2023).
chondrosarcoma (5 papers, 2005 to 2022). A malignant cartilaginous matrix-producing mesenchymal neoplasm arising from the bone and soft tissue. "Moreover, several investigators have found that the measurement of MCM6 protein expression is a good diagnostic marker for chondrosarcoma, and lymphoma." (PMID 25046975, 2014).
lactose intolerance (5 papers, 2017 to 2024). "Among GG homozygotes of the rs4988235 polymorphism of the MCM6 gene, i.e., among the patients with lactose intolerance, lower BDMs were described, especially in the vertebral range (BDM TH)." (PMID 39275317, 2024). "It was demonstrated that in the population of women after menopause, the carriage of the G allele of the rs4988235 polymorphism of the MCM6 gene, i.e., among the patients with lactose intolerance, significantly increased the risk of developing type-2 diabetes." (PMID 39275317, 2024). "In our study group, it was further observed that women with the GG homozygote of the rs4988235 polymorphism of the MCM6 gene consumed significantly less calcium (milk/sugar), which was probably related to the observed lactose intolerance." (PMID 39275317, 2024). "The results of our study remain consistent, in terms of the frequency of the rs4988235 polymorphism of the MCM6 gene and lactose intolerance, with the results obtained in a group of 63 young Polish adults." (PMID 39275317, 2024). "In the present study, genetic profiling for lactose intolerance was performed by determining the rs4988235 variant of the MCM6 gene in 607 female patients after menopause." (PMID 39275317, 2024). "One of the genetic factors predisposing individuals to lactose intolerance is rs4988235 polymorphism of the MCM6 gene." (PMID 39275317, 2024). "It was also found that the GG homozygotes of the rs4988235 polymorphism of the MCM6 gene were significantly more likely to develop type-2 diabetes; thus, lactose intolerance associated with the MCM6 gene variant studied may be considered a risk factor for the development of type-2 diabetes." (PMID 39275317, 2024). "Mutations in the MCM6 gene can lead to lactose intolerance, lactose non-persistence and metabolically unhealthy obesity in children." (PMID 38773180, 2024). "The complex MCM6/LCT variation also participated in several diseases’ progress such as obesity, lactose intolerance, and irritable bowel syndrome." (PMID 37063923, 2023).
liver cancer (5 papers, 2018 to 2021). An epithelial or non-epithelial malignant neoplasm that arises from the liver. "Little was previously known about MCM2 and MCM6 protein expression in liver cancer, we observed their up-regulation in HCC." (PMID 29463213, 2018). "Importantly, only a few genes were previously implicated with liver cancer development (ATG4B, CCR5, MCM6, and UCN), whereas most of the epidrivers were newly identified." (PMID 34375307, 2021). "MCM6, CDC20, and PCNA are also associated with prognosis in liver cancer." (PMID 32082966, 2019). "Genes like GTSE1, CDC20, PCNA, and MCM6 may be promising prognostic molecular biomarkers in liver cancer." (PMID 32082966, 2019). "Among the DEGs, CDC20, PCNA, and MCM6 might synergistically affect regulations in cell cycle with GTSE1 and might be potential prognostic predictors in liver cancer." (PMID 32082966, 2019).
non-small cell lung carcinoma (5 papers, 2019 to 2025). A group of at least three distinct histological types of lung cancer, including non-small cell squamous cell carcinoma, adenocarcinoma, and large cell carcinoma. "Patients with a high level of MCM6 were found to have poorer survival and a higher risk of death in craniopharyngioma, non-small cell lung cancer, and mantle cell lymphoma." (PMID 34993142, 2021). "In non-small cell lung carcinoma, MCM6 expression was upregulated as well 12, while in gastric cancer, there have been few studies to determine the potential involvement of MCM6." (PMID 31528213, 2019). "IFT57 exerts an oncogenic role in non-small cell lung cancer by activating DNA replication and cell cycle pathways via upregulation of MCM2, MCM6, and MCM8 expression." (PMID 40145017, 2025).
Obesity (5 papers, 2021 to 2024). Accumulation of substantial excess body fat. "Recent advances in genomic research have identified several single nucleotide polymorphisms (SNPs) in genes such as FTO, MCM6, HLA, and MC4R, associated with obesity." (PMID 38035352, 2023).
prostate carcinoma (5 papers, 2017 to 2021). A carcinoma that arises from epithelial cells of the prostate gland. "Here, we report that MCM2, MCM3, MCM4, and MCM6 (MCM2/3/4/6) are elevated in human NEPC and high levels of MCM2/3/4/6 are associated with liver metastasis and poor survival in prostate cancer patients." (PMID 34172788, 2021). "While MCM6 was reported to be prognostic marker in a few malignancies, MCM7 is extensively studied in human prostate cancer tissues and is correlated with higher propensities for prostate cancer progression, invasion, and metastasis." (PMID 28424404, 2017).
colorectal cancer (4 papers, 2019 to 2025). A primary or metastatic malignant neoplasm that affects the colon or rectum. "Though, to the best of our knowledge, no investigation of the clinical relevance in terms of clinical outcome of MCM6 in colorectal carcinoma patients in a representative cohort has been published." (PMID 31072339, 2019). "We here applied IHC of Topo II α and MCM6 to a large and representative cohort of patients diagnosed with colorectal carcinoma." (PMID 31072339, 2019).
gastric cancer (4 papers, 2019 to 2025). A primary or metastatic malignant neoplasm involving the stomach. "For example, YAP can induce MCM6 transcription in gastric cancer by maintaining a complex with the small chromosome 6 MCM6 promoter." (PMID 40723817, 2025). "Prognostic analysis showed that the combined expression of CDK5RAP3 and MCM6 was an independent prognostic factor correlating with the overall survival of gastric cancer patients." (PMID 31528213, 2019). "When CDK5RAP3 expression was low, gastric cancer patients with low expression of MCM6 had a better prognosis than did those with high CDK5RAP3 expression (P<0.05)." (PMID 31528213, 2019). "We discovered that CDK5RAP3 could interact with MCM6 and prevent it from translocating into the nucleus in gastric cancer." (PMID 31528213, 2019). "In summary, our results clarified that CDK5RAP3 interacts with MCM6 and prevents MCM6 from entering the nucleus, thereby influencing the proliferation of gastric cancer, which provides a new aspect of how CDK5RAP3 may suppress tumor proliferation." (PMID 31528213, 2019). "Notably, elevated MCM6 expression correlates with poor survival in gastric cancer patients." (PMID 41049004, 2025). "But MCM6 supports YAP by activating the PI3K/Akt/GSK-3β signaling pathway, which overactivates YAP and enhances the occurrence and metastasis of gastric cancer." (PMID 40723817, 2025). "Significantly, MCM6 and CDK5RAP3 together influenced the prognostic value of patients with gastric cancer, which provided clinical support that MCM6 is involved in the tumor suppression mechanism of CDK5RAP3." (PMID 31528213, 2019). "Our results demonstrate that CDK5RAP3 can interact with MCM6 and prevent MCM6 from translocating into the nucleus, which may be a potential mechanism through which CDK5RAP3 negatively regulates the proliferation of gastric cancer." (PMID 31528213, 2019). "What's more, in our manuscript we focused on the relationship between MCM6, CDK5RAP3, clinicopathological data and prognosis of the patient, thus we just selected the most representative gastric cancer cell lines of HGC-27 and AGS to find some change in phenotype." (PMID 31528213, 2019). "In gastric cancer samples, the staining of MCM6 was mostly in the nucleus, while in the adjacent nontumor tissues, the staining revealed that MCM6 remained in the cytoplasm." (PMID 31528213, 2019). "Furthermore, knockdown of MCM6 reversed the effect of CDK5RAP3 downregulation in HGC-27 and AGS cells, which indicates that MCM6 could mediate the tumor suppressor role of CDK5RAP3 in gastric cancer." (PMID 31528213, 2019). "There are few studies investigating the role of MCM6 in gastric cancer, and the interaction of CDK5RAP3 and MCM6 had not been investigated." (PMID 31528213, 2019).
mantle cell lymphoma (4 papers, 2005 to 2022). Mantle cell lymphoma is a rare form of malignant non-Hodgkin lymphoma affecting B lymphocytes in the lymph nodes in a region called the ``mantle zone''. "Since the level of cell proliferation is the most valuable predictor of survival in mantle cell lymphoma (MCL), we investigated lymph node biopsy specimens from 70 patients immunohistochemically with a monoclonal antibody against MCM6." (PMID 16189522, 2005).
pancreatic cancer (4 papers, 2021 to 2025). "Consistent with our findings, the role of YAP/TEAD2 complex in driving MCM6 expression at the transcriptional level was depicted in pancreatic cancer." (PMID 36185598, 2022). "MCM genes including MCM2, MCM5 and MCM6 were upregulated in pancreatic cancer and show strong positive coexistence with each other." (PMID 33507917, 2021).
Bladder Cancer (3 papers, 2024). "Clinical tumor diagnostic markers for BC include Bladder Tumor Antigen (BTA), urine cytology (UroVysion), Urothelial Cancer-Associated Antigen 1 (UCA1), Cytokeratin-19 Fragment (CYFRA 21-1), and Bladder Cancer MCM6 marker." (PMID 39071712, 2024).
breast tumors (3 papers, 2017 to 2022). "Thereby, it seems that MCM6 is capable of more precise classification of breast tumors regarding histologic and mitotic grades." (PMID 35125121, 2022). "Mcm6 and Ncapd2 are E2F targets as well, and little is known about their roles in breast tumor progression." (PMID 28212608, 2017).